EGFR (epidermal growth factor receptor)
Diseases named in the same sentence as EGFR in open-access papers (continued):
Sharing a sentence is not in itself a finding about the gene and the disease.
tumor (continued). "The Classical glioma subtype has an astrocytic signature; EGFR amplification is commonly observed in this tumor type as well as high expression of Nestin (a neural precursor and stem cell marker), and Notch and Sonic hedgehog signaling pathways." (PMID 25955030, 2015). "In NSCLC, despite an initial response, resistance to EGFR-TKIs will occur and thereafter tumor progresses." (PMID 26227959, 2015). "In the present study, 25 tumor samples (13 obtained before and 12 after EGFR-TKI treatment) from 18 NSCLC patients with activating EGFR mutations were evaluated for T790M with dPCR." (PMID 26015401, 2015). "Using an EGFR mutation (I706Q, V948R) that perturbs the ability of EGFR to dimerize intracellularly, we showed that a modest drug-induced increase in the fraction/stability of the EGFR homodimer may have a significant biological impact on the tumor cell’s proliferation potential." (PMID 25762314, 2015). "Despite targeting EGFR using various strategies to abrogate tumor growth in preclinical studies, however, only a subset of patients showed responses to EGFR inhibitors, including cetuximab." (PMID 26655729, 2015). "Silencing TRB3 not only decreased the basal level of critical tumour-promoting factors such as EGFR, COX2, MMP1, MMP-2, MT-MMP, Snail, Twist and c-Myc but also protected them from the IGF-1 induction." (PMID 26268733, 2015). "As a consequence of the gain of EGFR and the loss of HER3, tumor vasculature responds to EGFR ligands." (PMID 25884419, 2015). "As its name suggests, EGFR regulates cell growth, survival, proliferation and differentiation and plays a complex and crucial role in embryonic development and in tumor progression." (PMID 26161544, 2015). "RTK profile analysis using collaborative enzyme enhanced reactive-immunoassay (CEERTM) was performed on tumor specimens collected from 34 patients who received EGFR TKIs." (PMID 26439803, 2015). "The treatment with EGFR-inhibitors is currently in clinical practice, having demonstrated important anti-tumor activity in patients with head and neck squamous cell carcinoma, metastatic colorectal cancer, lung cancer as well as breast cancer." (PMID 25991665, 2015). "Clinical follow-up studies will have to reevaluate the use of EGFR inhibitors in HCC and restrict it to patients with EGFR expression in liver macrophages, since we would expect a worse outcome in patients where the EGFR is expressed in tumor cells." (PMID 26729094, 2015). "Blocking AR/EGFR signaling in Tregs with Gefitinib also enhanced anti-tumor immunity and decreased tumor size in a mouse xenograft tumor model." (PMID 26451607, 2015). "Inhibition of both c-Met and EGFR oncogenic pathways provides superior suppression of HCC tumor growth." (PMID 26000702, 2015). "Mechanistically, a feedback activation of EGFR was identified upon BRAF inhibition in BRAFm CRC supporting persistent tumor cell proliferation through reactivation of the MAPK and PI3K pathways." (PMID 26617477, 2015). "NIR-PIT for TNBC was effective regardless of expression of EGFR, however, greater cell killing was shown with higher EGFR expression tumor in vitro." (PMID 26313651, 2015). "In two different mouse tumor growth models, we also found that WB-308 therapeutically blocked NSCLC tumor growth by suppressing the EGFR signaling pathway." (PMID 25730907, 2015). "Tumor sections stained for EGFR, HER2 and HER3 showed markedly reduced receptor expression after only one dose of Pan-HER treatment compared with vehicle treated tumor sections." (PMID 26460961, 2015). "The patients with tumor displaying the phenotype EGFR+/EGF+ had a significantly impaired OS compared to those with EGFR+/EGF− (48.1% versus 84.2%; p < 0.000; Fisher's exact test)." (PMID 26634172, 2015). "The CD44H (hyaluronian receptors), CD44v6, CCR6 (chemokine receptors) and EGFR (epithelial growth factor receptor) are involved in interactions of tumour cells with monocytes." (PMID 26626416, 2015).
tumor (continued). "COX-2 and fibronectin levels were increased upon the activation of EGFR signaling, leading to tumor metastasis." (PMID 25595899, 2015). "Similar mutations and KRAS gene amplification have been shown to confer secondary resistance to anti-EGFR treatment in the same tumor type." (PMID 25691052, 2015). "Tumor growth was significantly inhibited by erlotinib exclusively in xenografts derived from EGFR-activated LCSCs, supporting the results in vitro." (PMID 26247735, 2015). "Accumulating evidence has revealed that miRNAs are oncomirs or tumor suppressors by targeting the EGFR signaling pathway in different types of cancer." (PMID 26273639, 2015). "Additional staining for cytokeratin 5/6 (KRT5/6), epidermal growth factor receptor (EGFR) and Ki-67 has also been used as a surrogate for gene expression profiling to allocate tumours to luminal A, luminal B, HER2 or basal-like molecular subtypes." (PMID 25633981, 2015). "As a consequence, these tumours were highly sensitive to the EGFR-tyrosine kinase inhibitors (TKIs)." (PMID 25683726, 2015). "Here, we investigate the efficacy of EGFR inhibitor nimotuzumab in combination with PDT to effectively treat oral tumor xenografts in vivo." (PMID 25918252, 2015). "Consistent with our findings, erlotinib combined with pertuzumab has been shown to surpass single therapy in inhibiting tumor activity in a NSCLC xenograft model with high EGFR protein expression (QG-56 cells)." (PMID 25992771, 2015). "The exceptional activity of the inhibitor in EGFR-T790M cells was further confirmed in three-dimensional tumor spheroids derived from NCI-H1975 cells." (PMID 26015408, 2015). "Despite the pitfalls in EGFR IHC, EGFR remains one of the most commonly investigated cancer biomarkers due to its oncogenic role in various tumour types." (PMID 26149458, 2015). "The epidermal growth factor receptor (EGFR) superfamily has been identified in the development of tumor cells and as such has emerged as a therapeutic target." (PMID 26096604, 2015). "The exact underlying mechanism on EGFR-mediated immune suppression remained unclear, albeit that ERK1/2 signalling was shown to be involved in regulating cytokine production and skin inflammation." (PMID 26055519, 2015). "Pre-clinical results demonstrate the ability of TKIs to inhibit tumor cell growth, angiogenesis, survival, and proliferation in several different EGFR transfected GBM cell lines." (PMID 25688333, 2015). "The modulation of the steady state of RTKs like HER2 and EGFR by neuropeptides such as SP can influence the clinical response of a tumor." (PMID 26114632, 2015). "There was a marked decrease in EGFR expression in the SCLC resistant tumours compared with baseline, but EGFR expression was intact in resistant EGFR mutant NSCLCs." (PMID 25758528, 2015). "The affinity of E. coli cells displaying the antibody fragment towards tumor cells overexpressing EGFR was demonstrated in FACS and fluorescence microscopic assays." (PMID 26712767, 2015). "Although EGFR inhibition reduces mPGES-1SC and mPGES-1KD cell xenograft tumour growth, we show that mPGES-1/PGE2 signalling sensitizes tumour cells to EGFR inhibitors." (PMID 26113609, 2015). "Although T790M was present in all pre-TKI samples from 13 patients, 10 of these patients had a low T/A ratio and manifested substantial tumor shrinkage during treatment with EGFR-TKIs." (PMID 26015401, 2015). "The EGFR signaling pathway is an important target in anticancer drug development, in view of its role in regulation of tumor cell proliferation and apoptosis." (PMID 26079945, 2015). "Western blot analysis on tumor samples from mice sacrificed on day 14, after 1 week of treatment, demonstrated that saracatinib reduces EGFR phosphorylation similar to that observed with erlotinib, whereas dasatinib failed to do so." (PMID 26325669, 2015).
tumor (continued). "Canine anti-EGFR was shown to decrease canine mammary carcinoma cell proliferation by 40%–60% and to mediate tumor cell killing by macrophage phagocytosis in vitro." (PMID 27066495, 2015). "Of the 14 tumour samples for which the EGFR methylation analysis was performed on the primary and metastatic lesions, the results demonstrated heterogeneity between the two specimens." (PMID 25663927, 2015). "The interaction of galectin-3 with cell surface epidermal growth factor receptor (EGFR) and transforming growth factor-β receptor (TGFβR) is also believed to contribute to the increased invasiveness of tumor cells." (PMID 25669973, 2015). "Conversely, the H4 Y72 peptide disrupted EGFR-histone H4 interaction and was able to suppress breast cancer xenograft tumor growth." (PMID 26546517, 2015). "After approximately 1 month of growth, the tumor implants (ranging in size from 0.5–1.0 cm in diameter) were resected and topically stained for 10 min with an equimolar mixture of EGFR-targeted and untargeted (isotype-control) SERS NPs." (PMID 25716578, 2015). "Several other studies show a proangiogenic and tumor supporting effect of EGFR signaling inside the tumor vasculature." (PMID 25884419, 2015). "Studies have shown that EGFR-activated cell signaling plays important roles in lung tumorigenesis and tumor progression." (PMID 25869210, 2015). "Reversible small molecule inhibitors of EGFR, such as gefitinib and erlotinib, exert anti-tumor activity in heavily pretreated NSCLC patients with few side effects and were initially approved for 2nd/3rd line settings." (PMID 26439803, 2015). "As tumor concentrations of lapatinib increased to 2 μM, decreased p-EGFR and p-HER2 were apparent coincident with increasing p-HER3, presumably reflecting inhibition." (PMID 26571496, 2015). "We evaluated individual tumor responses to EGFR-TKIs in patients whose tumors were of measurable sizes." (PMID 25823662, 2015). "Pulsed-mode ultrasound (pUS) exposure therapy was recently shown to enhance the anti-tumor effect of an EGFR-targeting chemotherapeutic drug in colon-cancer-bearing mice." (PMID 25960704, 2015). "Global metaanalysis of EGFR inhibitor-resistant vs. sensitive cell lines presented here identifies the transcriptional and metabolic differences that allow tumor cells to evade EGFR-targeted therapies." (PMID 25948104, 2015). "It is essential to recognize that a gene/protein can be a driver in some patients within a given tumor type (EGFR amplification) yet more commonly only a minor wheel (or even a bystander) in the majority of patients with that same tumor type." (PMID 25557400, 2015). "Several vaccines target tumor specific antigens, as those against melanoma-associated antigen-A3 (MAGE-3), MUC-1, EGFR, human telomerase reverse transcriptase (hTERT) or NY-ESO-1." (PMID 26487966, 2015). "Tumor expression of ducto-luminal (K8/18) and ducto-basal (K14) cells was maintained along with K6 and EGFR." (PMID 25195860, 2015). "An inhibition of miR-21 induced apoptosis in PC9R cells and suppressed tumor growth in nude mice treated with EGFR-TKI." (PMID 26273639, 2015). "Because of the central role that metabolism plays in tumour biology, we explore here the metabolic features of EGFR TKI sensitivity in CALS and CALR cells grown as 2D monolayers, 3D spheroids and tumour xenografts by using NMR spectroscopy." (PMID 25742484, 2015). "Nimotuzumab is a potent EGFR inhibitor that requires bivalent binding for stable attachment and would therefore bind preferentially to tumor cells having a medium to high surface density of EGFR protein." (PMID 25918252, 2015). "In the present study, the expression of EGFR was determined in prospectively collected tumor tissues from a cohort of AdCC and pleomorphic adenoma (PMA) patients treated with surgery; the expression of EGFR was also detected in normal parotid glands." (PMID 25997612, 2015).
tumor (continued). "This suggests that partial inhibition of EGFR is sufficient to contribute to suppression of tumor growth when BRAFV600E is being inhibited." (PMID 26023796, 2015). "EGFR is expressed in various types of neoplasia including those in the lung, head and neck, colon, pancreas, breast, ovary, bladder and kidney as well as in gliomas." (PMID 25629807, 2015). "The ErbB family members: EGFR, ErbB2, ErbB3, and ErbB4 receptors are established as drivers of many aspects of tumor initiation and progression to metastasis." (PMID 25699077, 2015). "Although some delay in tumor progression has been noted in patients with wildtype EGFR, this population is generally unresponsive to erlotinib." (PMID 26053020, 2015). "For example, the interactions between Cetuximab with cancer cell EGFR and NK cell FcδR IIIa enhances cross-presentation of tumor Ags, such as EGFR by DC to cytotoxic T lymphocytes." (PMID 25674087, 2015). "EGFR mutation, KRAS mutation and ALK expression were investigated in 14 patients whose tumor specimens were available." (PMID 26682906, 2015). "We chose to target EGFR (Kin-1) andc-Src (Kin-2), two tyrosine kinases known to synergize to promote tumour growthand progression." (PMID 25658745, 2015). "In vitro study, WST-1 assay and Western blot analysis revealed that EGFR expression levels were correlated with tumor cell viability." (PMID 26673416, 2015). "In contrast, mutant EGFR expression increased invasive potential, migratory ability and the rate of xenograft tumour formation from MCF10CA1a cells significantly compared to the control empty vector or wild type EGFR-expressing MCF10CA1a cells." (PMID 25969993, 2015). "Cetuximab is a chimeric human-murine monoclonal antibody that competitively binds to the accessible extracellular domain of EGFR and inhibits dimerisation and subsequently inhibits cell proliferation, tumor growth and metastasis." (PMID 25918252, 2015). "Tumours with ALK fusion mutations are responsive to the tyrosine kinase inhibitor crizotinib however, as with EGFR mutations and TKIs, resistance develops with evidence of secondary ALK point mutations and activation of EGFR signalling in some cases." (PMID 26101870, 2015). "By week 7 tumours treated with cetuximab had shrunk by 70% but were still palpable; on the contrary those who received EGFR-MEK combo blockade were undetectable." (PMID 26392303, 2015). "The in vivo xenograft studies further confirm that monensin effectively inhibits xenograft tumor growth by inhibiting cell proliferation through targeting EGFR signaling." (PMID 26639992, 2015). "But the small amount of MET-amplified cells can be expanded by the selective pressure of anti-EGFR moAbs and they can induce acquired resistance, as they become the leading tumor cell population." (PMID 26318427, 2015). "This literature review aimed to describe the level of mutation status concordance between primary and corresponding metastatic tumours, considering EGFR, KRAS and any other molecular aberrations noted." (PMID 26338018, 2015). "All these results suggested that the HDAC9-promoted proliferation and tumor formation of GBM cells were possibly mediated by potentiating the EGFR signaling pathway." (PMID 25760078, 2015). "EGFR and phospho-AKT staining showed associations with tumor grade and/or lymph node status (P < 0.05)." (PMID 26209091, 2015). "Nevertheless, in metastatic renal cell carcinoma (RCC), membranous EGFR is highly present in the tumor sample and higher cytosolic EGFR expression was in the paired normal renal tissue." (PMID 26497368, 2015). "High sensitivity dPCR and NGS platforms are able to pick up circulating tumor RAS mutations and other molecular alterations in plasma that drive primary or acquired resistance during anti-epidermal growth factor receptor (EGFR) treatment." (PMID 26669312, 2015).
tumor (continued). "In this study, we evaluated the Artemis system and assessed the minimal detection limit of tumor-specific imaging using an EGFR-targeting nanobody." (PMID 25344146, 2015). "The EGFR signaling pathway has been shown to promote tumor progression in many types of human cancers." (PMID 25730907, 2015). "Molecular mechanisms of TNBC cell invasion and tumor metastasis are beginning to emerge, with signaling by EGFR and Src kinases as key players and potential therapeutic targets." (PMID 25823823, 2015). "Not only do plasma levels of lapatinib underestimate corresponding concentrations in tumor and normal EGFR expressing tissues, but multiple determinants of tumor concentration complicate this relationship making predictions difficult." (PMID 26571496, 2015). "We have previously reported that combined therapy with PDT and the EGFR inhibitor cetuximab inhibited tumor growth in a bladder human cancer model." (PMID 25918252, 2015). "Immunohistochemical studies revealed that mPGES-1 in human prostate tissues is correlated with EGFR expression in advanced tumours." (PMID 26113609, 2015). "The first study published reported that 38% of patients treated with the anti-EGFR monoclonal antibody cetuximab, who were known to have wt KRAS on the basis of tumor tissue analysis, later developed KRAS mutations." (PMID 25980577, 2015). "Erlotinib primarily targets the epidermal growth factor receptor (EGFR), and was shown to have optimal use in the neoadjuvant setting, resulting in downstaging of the tumor prior to surgery." (PMID 25909217, 2015). "In 8 NA samples, two of which (with less than 5% and 100 tumor cells) EGFR MUT, the analysis performed in a second A specimen confirmed the 2 MUT and the 6 WT (data not shown)." (PMID 25844806, 2015). "Here we used the endocytosis and subcellular trafficking of EGFR complexes in A431 monolayer culture and tumour spheroids as a model system for instrument validation." (PMID 26219252, 2015). "Because EGFR/PI3K/Akt/mTOR signaling promotes tumor cell proliferation, we next examined the effect of PROG and TMZ on the cell proliferation marker PCNA, which is often used for grading different neoplasms." (PMID 26110872, 2015). "We then demonstrate tracking of epidermal growth factor receptor (EGFR) complexes tagged with fluorescent beads in tumour spheroids, demonstrating deep 3D SPT in multicellular models." (PMID 26219252, 2015). "EGFR inhibitors and radiotherapy have a synergistic anti-tumor activity, but radiotherapy increases EGFRI side effects." (PMID 26361513, 2015). "Most of these pathways are regulated simultaneously by EGFR activation and involved in tumor invasion and metastasis." (PMID 26182292, 2015). "Deregulated transcriptional programs were characterized by growth and tumor promoting signals, with in particular the overexpression of EGFR, PDGFR and VEGF pathways, recognized as some of the main pathways driving TNBC." (PMID 25961742, 2015). "In tumor xenograft mouse models, erlotinib clearly reduced the growth of tumors with high levels of EGFR expression." (PMID 26673416, 2015). "To determine the impact of EZN4150-mediated p110α ablation on HER2+ tumor cell response to the EGFR/HER2 tyrosine kinase inhibitor (TKI) lapatinib, we treated SKBR3, BT474, and UACC893 cells with EZN4150 in the presence or absence of lapatinib." (PMID 26637440, 2015). "In patients treated with cetuximab, histopathological analysis of the tumor specimens at surgery showed reduced tumor cellularity, downregulation of tumor proliferation and decreased phospho-EGFR compared to untreated controls." (PMID 26437222, 2015). "Higher microvessel density was observed in HCC patient samples with EGFR-positive tumor endothelial cells." (PMID 26729094, 2015). "Next, gene expression of factors relating to EGFR signaling in tumor samples and their control counterparts were analyzed by quantitative RT-PCR." (PMID 26289340, 2015).